THBS4 (thrombospondin 4)
Diseases named in the same sentence as THBS4 in open-access papers (continued):
Sharing a sentence is not in itself a finding about the gene and the disease.
cancer (35 papers, 2010 to 2026). A tumor composed of atypical neoplastic, often pleomorphic cells that invade other tissues. "In gastric tumors, thrombospondin 4 is secreted by CAFs in high quantities, with transcription stimulated by tumor cells, and this is associated with cancer metastasis." (PMID 36765749, 2023). "Additionally, the correlation between THBS4 expression and cancer-associated fibroblasts (CAFs), specifically the PDGFRA+ inflammatory CAFs, was investigated to understand the stromal regulatory protein’s role in PTMC aggressiveness." (PMID 40303998, 2025). "The alteration of MFAP5 protein and THBS4 protein from fibroblast might be associated with the migration of ENCC—similar to the cancer cells." (PMID 36738110, 2023). "THBS4 is an extracellular calcium-binding protein involved in cell-to-cell and cell-to-matrix interactions, and was found to be overexpressed in cancer-associated stroma of diffuse-type gastric ADC secreted by cancer-associated fibroblasts, and in the stroma of invasive breast cancer." (PMID 35197508, 2022). "Despite extensive research on Thbs4 in cancer, angiogenesis, and cardiovascular diseases, its role in the nervous system, particularly in DRG neurons, remains understudied." (PMID 41153662, 2025). "In gallbladder cancer, CAFs-secreted THBS4 promotes cancer cell proliferation and EMT by activating Akt and phosphorylating HSF1." (PMID 38827236, 2024). "THBS3 and THBS4 expression exhibited the same trend in most cancer types, albeit with variable degrees of significance in cancer types." (PMID 39732719, 2024). "There is emerging evidence suggesting the involvement of thrombospondin 4 in gastric, breast and prostate cancers." (PMID 36765749, 2023). "In another type of cancer (prostate cancer), THBS4 was also found to maintain cancer stem cell-like properties via the PI3K/AKT pathway." (PMID 38201290, 2023). "THBS4 however significantly affects survival in cancers with “low” (bottom 25 percentile) relative to “high” (top 75 percentile)." (PMID 36190948, 2022). "Increased migration of fibroblasts in response to THBS4 stimulation is likely mediated through upregulation of transcription factor FOXH1 that has been shown to promote cancer cell proliferation and migration via activation of Wnt/β-catenin signaling pathway." (PMID 34631719, 2021). "Using the TCGA PanCancerAtlas for Mutual Exclusivity analysis of pan-cancer mutations, we uncovered cooccurrence relationships of THBS2, THBS4, and THBS5 with THBS1; THBS4, THBS3, and THBS5 with THBS2; and THBS3 and THBS4 with THBS5." (PMID 34804159, 2021). "Recent studies with bladder cancer cells have shown that THBS4 is able to promote cancer progression by enhancing cell proliferation, migration and invasion by activating the AKT signaling pathway." (PMID 34631719, 2021). "There is increasing data to support the role of THBS4 in cancer biology, especially in gastrointestinal and prostate tumors." (PMID 32899998, 2020). "Although THBS4 is reportedly frequently expressed in solid tumors, there are few reports of the clinicopathological features of carcinomas with THBS4 expression." (PMID 31703077, 2019). "THBS4 methylation is higher in cancers that also exhibit the CIMP phenotype, which is demonstrated by the strong correlation with the Laird panel of methylation markers." (PMID 20846368, 2010). "They hypothesized that the downregulation of miR-142-3p increased THBS4 expression, which could stimulate tumor angiogenesis, cancer cell migration, and vascular invasion." (PMID 38201290, 2023). "The invasion of cancer cells can be facilitated by activated stromal response, as has been shown in breast tumors where thrombospondin 4 expression was significantly upregulated in both invasive ductal carcinoma and invasive lobular carcinoma compared to normal stroma." (PMID 36765749, 2023). "THBS4 affects cancer stem cell-like properties in PCa by its regulation of the PI3K/Akt pathway." (PMID 37965470, 2023).
cancer (continued). "Likewise, Thrombospondin-4 (THBS4) was one of the most upregulated genes in DGC, which was correlated with cancer-associated fibroblasts in GC to stimulate EMT, as we previously reported." (PMID 35705840, 2022). "In HCC, THBS4 promotes cancer progression via FAK/PI3K/AKT pathway." (PMID 34804159, 2021). "Furthermore, high levels of THBS4 protein have been found in several pathological processes such as cancers, cardiovascular damage and remodeling as well as liver regeneration." (PMID 34631719, 2021). "It is speculated that TGF-β derived from cancer cells stimulated THBS4 expression on CAFs resulting in angiogenesis and cancer progression." (PMID 31703077, 2019). "Our data suggest that THBS4 might be involved in regulating cancer cell EMT phenotypes." (PMID 34804159, 2021). "Our findings revealed that cancer had lower expression of THBS1, THBS3, and THBS4 compared to normal tissue, whereas the expression of THBS2 was higher." (PMID 38827236, 2024). "These include: CDH1, MUC1, THBS4, and MSLN for PEs related to cancer; ADA2, CXCL10, and WARS for TB-PEs; CRP, S100A9, and VIM for parapneumonic PEs; and C9, LDHA, HPX, LDHB, and C3 for benign-PEs." (PMID 35197508, 2022). "Recent cancer studies have found that the thrombospondin (THBS) family, including THBS1, THBS2, THBS3, THBS4, and THBS5, play vital roles in the development and progression of human cancers." (PMID 34804159, 2021). "The active role of THBS4 in regulation of cell motility and proliferation was further supported by the downregulation of NPY1R, which was shown to inhibit cancer cell proliferation, migration and invasiveness." (PMID 34631719, 2021). "In contrast, THBS4 mRNA expression is lower in colorectal tumors compared to matched normal tissues, with the protein typically absent from normal epithelial and cancer cells." (PMID 36765749, 2023). "It needs to be further explored whether other THBS genes, including THBS3, THBS4, and THBS5, participate in modulating cancer cell EMT and metastasis in the future study." (PMID 34804159, 2021). "In fact, the western blotting indicated that THBS4 was expressed from CAFs, but not from NFs and cancer cell lines." (PMID 31703077, 2019). "THBS4 is expressed on stromal cells with αSMA or Podoplanin expression in the GC microenvironment, but not expressed on cancer cells with cytokeratin expression." (PMID 31703077, 2019). "THBS4 was stained at the cytoplasm and the cell membrane of stroma cells, but cancer cells with cytokeratin expression did not express THBS4." (PMID 31703077, 2019). "Reduced THBS4 expression levels did not correlate with a THBS4 PMR of 10 or greater in either cancers or cell lines." (PMID 20846368, 2010). "The forced over-expression of THBS4 in cancer cell lines significantly suppresses their colony forming abilities and growth, regardless of their baseline THBS4 expression levels." (PMID 20846368, 2010). "The western blot analysis results showed that CAFs (but not NFs and cancer cells) expressed THBS4." (PMID 31703077, 2019). "In addition, thrombospondin-4 (THBS4) is a non-structural extracellular matrix molecule and has also been shown to promote cancer progression by modulating the PI3K/AKT pathway." (PMID 41387465, 2025).
cardiovascular disease (6 papers, 2005 to 2026). "As dysfunction of THBS4 and lack of cardiorespiratory fitness are both risk factors for cardiovascular disease, it is plausible that THBS4 plays a role in the cardioprotective effects of exercise." (PMID 16138928, 2005).
heart disease (3 papers, 2019 to 2024). "When exogenous compounds enter cells, abnormal Ca2+ metabolism in the ER leads to ERS and thus apoptosis, which has been reported to be a feature of DCM and other heart diseases.The protein encoded by the THBS4 gene belongs to the platelet-responsive protein family." (PMID 38699233, 2024). "However, Thbs3 is unique in that it functions opposite to Thbs1, Thbs2, and Thbs4, where it enhances cardiac pathology with disease stimulation, while mice deficient in Thbs3−/− were partially protected from cardiac disease." (PMID 30622267, 2019).
skeletal dysplasia (1 paper, 2015). Any Mendelian diseases that affects growth and development of the skeleton. "While mutations of Thbs5, better known as cartilage-oligomeric matrix protein (Comp), cause two different forms of skeletal dysplasia, the role of Thbs3 and Thbs4 in the skeleton are still poorly defined." (PMID 26629997, 2015).
THBS4 also shares sentences with these, for which no sentence is quoted: infection (5 papers); bladder cancer (4); Stroke (4); prostate carcinoma (3); cutaneous T cell lymphoma (2); glioma (2); spinal muscular atrophy (2); abdominal aortic aneurysm (1); bacterial infections (1); bone cancer (1); breast tumors (1); chronic lymphocytic leukemia (1); clear cell renal cell carcinoma (1); COVID-19 (1); depression (1); diabetic nephropathy (1); diabetic retinopathy (1); diffuse gastric adenocarcinoma (1); dilated cardiomyopathy (1); ductal carcinoma (1); dystrophin deficiency (1); encephalitis (1); essential hypertension (1); gestational diabetes mellitus (1); gestational hypertension (1); glioblastoma (1); hypertrophic cardiomyopathy (1); hypertrophy (1); infectious disease (1); Left ventricular dilatation (1).
A further 25 diseases each share a sentence with THBS4 in 1 paper.